EGFR (epidermal growth factor receptor)
Diseases named in the same sentence as EGFR in open-access papers (continued):
Sharing a sentence is not in itself a finding about the gene and the disease.
cancer (continued). "Additionally, CUR altered the expression of EGFR, microRNAs and autophagy in cancer stem cells." (PMID 37697969, 2023). "Second, we could not provide molecular evidence that EGFR inhibition is a key factor in the efficacy of afatinib against cancers with HER2 E401G mutation, due to the limited tissue and necrosis." (PMID 36690964, 2023). "Interestingly, EGFR overexpression also induces IGFBP-3 in cancer cell lines, supporting the idea that EGFR and the IGF-II autocrine signals might act synergistically in a variety of solid cancers." (PMID 38255147, 2023). "Another important therapeutic target is the epidermal growth factor receptor (EGFR), a transmembrane protein responsible for triggering signaling cascades associated with proliferation, angiogenesis, apoptosis, and metastasis; its overexpression is associated with the progression of some cancers." (PMID 37514119, 2023). "When the expression of molecules that regulate EGFR endophagocytosis circulation is significantly increased, the duration of EGFR activation can be prolonged, with the relocation of EGFR and adhesion receptors at specific membrane sites, thereby promoting the metastasis and invasion of cancer cells." (PMID 36899380, 2023). "Finally, we speculate that the in vitro testing of drug activity in the presence of blood serum of individual patients and a model cancer cell line can be beneficial for the personalization of EGFR-specific therapeutics." (PMID 37626832, 2023). "Therefore, CMTM8 acts as an attenuator of EGF-induced signaling by facilitating ligand-induced EGFR endocytosis and subsequent desensitization, indicating that the alteration of CMTM8 levels in cancer might affect EGFR signaling." (PMID 37345137, 2023). "Finally, when it comes to the field of cancer cell biology, it is well‐accepted that self‐sufficiency in growth signaling is a hallmark of all cancer cells; we show here how cells achieve such self‐sufficiency for the prototypical GF system, that is, EGF/EGFR." (PMID 36856068, 2023). "Importantly we found several tumors completely regress upon cSNX1.3 treatment, indicating it may be an effective therapy for EGFR-driven cancers." (PMID 36253541, 2023). "Therefore, in addition to TKI therapy, EGFR/HER2 trafficking may be an additional target for cancer treatment." (PMID 37752992, 2023). "This is not enough for the appearance of cancer thought, but the clonal advantage in these cells makes them prone to additional mutational events, such as the activation of the epidermal growth factor receptor (EGFR), NOTCH signaling or the recruitment of macrophages and pro-inflammatory factors." (PMID 37371030, 2023). "Moreover, HPV−ve (HPV−) cancers commonly present with a loss of chromosome 9p, responsible for the downregulation of p16 (CDKN2A) expression, and the duplication of chromosome 7p, promoting the epidermal growth factor receptor (EGFR) overexpression." (PMID 36980527, 2023). "Thus, in EGFR-dependent cancer cells, blocking the oncogenic signals may lead to cellular stress that stimulates both exosomal and apoptotic pathways." (PMID 37296932, 2023). "In the era of biomarker-driven personalized cancer therapy, several biomarkers have been proposed as prognostic and predictive factors in different cancers, such as KIT mutations in gastrointestinal stromal tumors, EGFR mutations in lung cancer, and HER2 overexpression in breast cancer." (PMID 36979671, 2023). "Furthermore, cancer characterized by resistance to EGFR therapy may represent a possible application of EGFR/COX2 inhibition therapy." (PMID 37190301, 2023). "Therefore, targeting EGFR is one of the directions to develop and design anti-cancer drugs." (PMID 36782251, 2023). "The mentioned study did not investigate cancers with EGFR mutations, so the number of participants with EGFR mutations remained unknown." (PMID 37131310, 2023). "However, clinical trials showed that the combined use of EGFR TKIs may offer new hope for the treatment of cancer." (PMID 37754201, 2023).
cancer (continued). "Mutations or overexpression of growth factor receptor (EGFR) or human growth factor receptor 2 (HER2), inactivating mutations in mTOR regulators gene such as TSC1 and TSC2, as well as the activating mutations in mTOR itself, are also detected across cancer types." (PMID 36765661, 2023). "Additionally, preclinical evidence suggests that the sensitivity of cancer cells to early generation EGFR-TKIs may be transient." (PMID 36765799, 2023). "The enhanced synergy of cancer cells harboring PRKDC mutation to the daunorubicin-EGFR inhibitor combination could result from inhibiting nonhomologous end joining-mediated DNA double-strand breaks repair." (PMID 37629110, 2023). "Genetic changes in EGFR may lead to the development of cancer." (PMID 37639911, 2023). "However, its two distinct isoforms in the regulation of EGFR/ERK signaling pathway in human cancers were unknown." (PMID 36717944, 2023). "Increased transcripts of heparin-binding EGF-like growth factor (HBEGF), a positive regulator of the epidermal growth factor receptor, and protein kinase B gene might overstimulate stress response pathways and cell survival in a way that could be damaging to cancer cells." (PMID 37834191, 2023). "In addition, an overexpression of CDC42 could also inhibit the degradation of EGFR, inducing an increased level of EGFR, which could lead to cancer progression." (PMID 36936942, 2023). "Moreover, there are several cancer markers, including epidermal growth factor receptor (EGFR), vascular endothelial growth factor (VEGF), αvβ3 integrin, carcinoembryonic antigen (CEA), folate receptors, transferrin receptors, somatostatin receptors, and prostate stimulating membrane antigen (PSMA)." (PMID 36765652, 2023). "Thus, a multidrug targeted therapy that exploits Sia acetyl group inhibitors (or acetyltransferase inhibitors) and EGFR inhibitors could be explored in cancer treatment." (PMID 37687086, 2023). "Furthermore, DLC1 could induce apoptosis, senescence and autophagy of cancer cells by regulating the EGFR/Akt/ NF-κB signalling pathway, and suppress the proliferation and migration of tumors by modulating DLC1/RhoA pathway." (PMID 37737712, 2023). "Notably, dysregulated EGF/EGFR signal activation is commonly found in cancers." (PMID 37132043, 2023). "Therefore, developing dual EGFR/BRAF inhibitors is a promising approach in cancer therapy." (PMID 38138441, 2023). "The Akt/PI3K/mTOR axis, which is among the vital downstream signaling pathways in cancer promotion, may be a promising find towards cancer therapy, even after EGFR activation, through involvement of a number of natural flavonoids and polyphenolic compounds, including curcumin." (PMID 36982245, 2023). "All the in vitro and in silico findings of the present research work against anti-HepG-2 cancer cell line and four key enzymes EGFR, PI3K, mTOR, and Tubulin polymerization conclude that the 2,5-dimethoxy based bromobenzofuran-oxadiazole BF-5 could be the potential lead anti-HepG2 cancer agent." (PMID 36769327, 2023). "The activation of EGFR has been identified as a mechanism through which GFs control normal and uncontrolled cellular function, and this has led to the development of EGFR inhibitors for cancer treatment and topical GF application to enhance cutaneous wound healing." (PMID 37735655, 2023). "Thus, after anti-EGFR drug-free intervals that allow for the clearance of resistant cancer cell clones, a rechallenge with EGFR inhibitors might represent an appealing therapeutic option in patients that benefit from prior anti-EGFR therapy." (PMID 37046778, 2023). "This review describes the interplay between the PGE2 cascade and epidermal growth factor receptor that fuel cancer progression, and new therapeutic strategies that target these signaling pathways, to outline the importance of the modulation of the inflammatory process in cancer fighting." (PMID 37190301, 2023).
cancer (continued). "Furthermore, EGFR-mediated cancers tend to be more aggressive." (PMID 37315787, 2023). "In addition to enhancing mutagenesis, ROS stimulates other signaling pathways that may lead to cancer, including epidermal growth factor receptor (EGFR) and mitogen-activated protein kinase (MAPK) signaling." (PMID 36831413, 2023). "Thus, EGFR/RAS/RAF/MEK/ERK pathway is an essential target in clinical cancer therapy." (PMID 36755950, 2023). "Similarly, the genomic analyses on receptor tyrosine kinases suggest that genes which are highly activated in response to binding with ligands, like EGFR signaling in cancer, have evolved in a way to be mutable—as measured by proximity to telomeres and A+T content." (PMID 37104389, 2023). "Indeed, therapy with anti-EGFR drugs removes RAS/BRAF-sensitive clones of the wild type (RAS/BRAF-wt), and the obtained RAS mutation-resistant clones become the majority population of cancer cells." (PMID 37927605, 2023). "Indeed, EGFR members and their ligands are expressed in sEVs released by cancer cells." (PMID 37296932, 2023). "Different EGFR gene and protein alterations have been proposed as potential prognostic indicators or therapy response predictors—that said, different types of aberrant EGFR expression patterns could be used to asses individual schedules of treatment in cancer patients." (PMID 37239035, 2023). "For example, the use of nanocomplex-based on gold nanoparticles (AuNPs) conjugated with anti-EGFR cetuximab by the immobilization of cetuximab on the AuNPs surfaces, demonstrated long-term stability, EGFR affinity and cancer cell death due to apoptosis of several cancer cells, including HNSCCs." (PMID 36980527, 2023). "While epithelial growth factor receptor (EGFR) is commonly overexpressed/genetically altered in human malignancy, it remains unknown whether targeting EGFR with tyrosine kinase inhibitor (TKI)-conjugated nanoparticles may direct NIR-PTT to cancers with cellular precision." (PMID 36291827, 2022). "Similarly, the pyruvate dehydrogenase kinase 1 (PDK1) inhibitor Cpd64, when combined with EGFR TKI, improved anti-cancer effects in EGFR-mutant NCI-H1975 and NCI-H1650 cell lines and in a xenograft mouse model via the improvement of oxidative phosphorylation and mitochondrial respiration." (PMID 36532721, 2022). "Importantly, studies from the Flores’ and Vousden’s groups demonstrated that TAp63 could suppress cancer metastasis via a coordinated up-regulation of Dicer and miR-130b and by blocking integrin recycling and EGFR, respectively." (PMID 35806218, 2022). "However, EGF-dependent signaling pathways also negatively regulate autophagy by activating the class I PI-3 kinase, which is a major upstream activator of mTORC1, and indeed, EGFR inhibition leads to an enhancement of autophagy in certain types of cancer cells." (PMID 36206843, 2022). "Notably, other important cancer proteins, such as EGFR (adj." (PMID 35457260, 2022). "Hence, the current study corroborates the previous literature for cocoa bioactives may have more affinity towards cancer cells to inhibit the EGFR task, which was demonstrated via docking studies." (PMID 35421091, 2022). "In cancers that may not necessarily show high rates of EGFR-activating mutations, deregulation can also occur through overexpression." (PMID 36185288, 2022). "Finally, because of the importance of EGFR/Src/β5-integrin in the physiology of cells and tissues, and the connection between dysregulation of these systems and cancer, FCLs likely play a broader role in coordinating the responses to chemical and mechanical stimuli." (PMID 35173166, 2022). "In addition, it has been found that RES directly decreases EGFR-mediated signaling, so it is reasonable to hypothesize that PD could inhibit cancer cell growth either directly or indirectly by reducing immunological escape mechanisms." (PMID 35955576, 2022). "Thus, targeting EGFR/AKT signaling is considered to be a crucial strategy of cancer therapy." (PMID 35504024, 2022).
cancer (continued). "Therefore, BIM upregulation appears to be essential for the induction of apoptosis but is not sufficient for apoptosis in EGFR-mutated cancer cells." (PMID 36553449, 2022). "However, the role of EGFR clusters in cancer and their dependence on EGF binding is unclear." (PMID 35612280, 2022). "Our studies suggested that loss of RBM10 could limit EGFR TKI–induced apoptosis rather than increase the proliferative capacity of cancer cells." (PMID 35579943, 2022). "Furthermore, the anti-cancer effects of capsaicin have been demonstrated by the inhibition of Epidermal Growth Factor Receptor (EGFR) and PI3K/Akt/mTOR signaling pathways, and through IL-6/Signal Transducer and Activator of Transcription- 3 (STAT-3)/Cyclin D1 (CCND1) and survivin pathways." (PMID 35600864, 2022). "We hypothesized that cancer patients from these four subgroup unions were unlikely to produce a favorable outcome upon treatment with EGFR inhibitors due to the lack of targetable mutations in this gene." (PMID 36230688, 2022). "Taking these results together, erlotinib–1,2,3-triazole derivative 3d could induce apoptosis and arrest cell cycle, and the combination of erlotinib and 1,2,3-triazole might be a successful strategy for the development of new EGFR inhibitors for cancer therapy." (PMID 35517789, 2022). "EGFR activation leads to downstream stimulation of multiple signaling cascades, including MAPK and phosphoinositide 3-kinases (PI3K)/protein kinase B (AKT), which are tightly associated with oncogenesis, proliferation, maintenance, migration, and survival of cancer cells." (PMID 35190588, 2022). "However, for patients whose cancer cells don’t express EGFR, an alternative target is necessary." (PMID 36185287, 2022). "Besides, activated EGFR signaling contributes to the upregulated PD-L1 on cancer cells, and EGFR-TKI might cooperate with α-PD-1/PD-L1 to attenuate immune evasion." (PMID 35062949, 2022). "Furthermore, it is worth exploring the efficacy of other therapeutic strategies against NECC: PD-L1 inhibitors and the combination of PD-1/PD-L1 inhibitors with therapeutic cancer vaccines, epidermal growth factor receptor tyrosine kinase inhibitors (EGFR-TKIs), or other targeted therapies." (PMID 36467090, 2022). "Because cancer cells expressed EGFR at high levels, the authors analysed cancer cell lines compared with fibroblasts and could confirm that the ubiquitination process is reduced in presence of a high abundance of EGFR." (PMID 35748700, 2022). "In addition, EGFR inhibitors have become a way for the cancer treatment." (PMID 35919181, 2022). "However, EGFR WT cancer patients may benefit from compounds that are used for immuno-targeted combination therapies, as was previously showed in EGFR WT NSCLC patients." (PMID 36230688, 2022). "Therefore, targeting YAP/TAZ such as by the use of TEAD inhibitors or inhibitors/antibodies for unknown mechanisms in combination with EGFR-targeting therapy may provide novel therapeutic approaches for preventing cancer recurrence and progression." (PMID 36294681, 2022). "Blocking the EGFR/MAPK signaling could protect cancer cells from ferroptosis." (PMID 35692844, 2022). "However, the EGFR-targeting antibodies are not effective in many cancers due to mutations in the EGFR and KRAS genes, and/or other intracellular signaling pathways." (PMID 36555466, 2022). "The inverse correlation between DHRS7 and EGFR expression and the increase in EGFR expression and phosphorylation following DHRS7 knockdown could be of therapeutic relevance as the loss of DHRS7 may alter the sensitivity of the cancer cells towards antibodies and inhibitors of EGFR." (PMID 35804847, 2022). "Proteins including progesterone receptor (PR), epidermal growth factor receptor (EGFR), mechanistic target of rapamycin (mTOR), p53R2, cytotoxic T-lymphocyte–associated antigen 4 (CTLA-4), cyclin dependent kinase-(CDK8), etc. can be used as therapeutic targets to stop cancer from progressing." (PMID 36235128, 2022).